LRRK2 (leucine rich repeat kinase 2)
Description:
Serine/threonine-protein kinase which phosphorylates a broad range of proteins involved in multiple processes such as neuronal plasticity, innate immunity, autophagy, and vesicle trafficking. Is a key regulator of RAB GTPases by regulating the GTP/GDP exchange and interaction partners of RABs through phosphorylation. Phosphorylates RAB3A, RAB3B, RAB3C, RAB3D, RAB5A, RAB5B, RAB5C, RAB8A, RAB8B, RAB10, RAB12, RAB29, RAB35, and RAB43. Regulates the RAB3IP-catalyzed GDP/GTP exchange for RAB8A through the phosphorylation of 'Thr-72' on RAB8A. Inhibits the interaction between RAB8A and GDI1 and/or GDI2 by phosphorylating 'Thr-72' on RAB8A. Regulates primary ciliogenesis through phosphorylation of RAB8A and RAB10, which promotes SHH signaling in the brain. Together with RAB29, plays a role in the retrograde trafficking pathway for recycling proteins, such as mannose-6-phosphate receptor (M6PR), between lysosomes and the Golgi apparatus in a retromer-dependent manner. Regulates neuronal process morphology in the intact central nervous system (CNS). Plays a role in synaptic vesicle trafficking. Plays an important role in recruiting SEC16A to endoplasmic reticulum exit sites (ERES) and in regulating ER to Golgi vesicle-mediated transport and ERES organization. Positively regulates autophagy through a calcium-dependent activation of the CaMKK/AMPK signaling pathway. The process involves activation of nicotinic acid adenine dinucleotide phosphate (NAADP) receptors, increase in lysosomal pH, and calcium release from lysosomes. Phosphorylates PRDX3. By phosphorylating APP on 'Thr-743', which promotes the production and the nuclear translocation of the APP intracellular domain (AICD), regulates dopaminergic neuron apoptosis. Acts as a positive regulator of innate immunity by mediating phosphorylation of RIPK2 downstream of NOD1 and NOD2, thereby enhancing RIPK2 activation. Independent of its kinase activity, inhibits the proteasomal degradation of MAPT, thus promoting MAPT oligomerization and secretion. In addition, has GTPase activity via its Roc domain which regulates LRRK2 kinase activity. Recruited by RAB29/RAB7L1 to overloaded lysosomes where it phosphorylates and stabilizes RAB8A and RAB10 which promote lysosomal content release and suppress lysosomal enlargement through the EHBP1 and EHBP1L1 effector proteins.
Synonyms: PARK8; ROCO2; DKFZp434H2111; FLJ45829; RIPK7; AURA17; DARDARIN
Tractability: Small molecule: a structure with a bound ligand is known; a high-quality ligand is known; it belongs to a druggable protein family. Antibody: UniProt places it where antibodies can reach, with high confidence; its Gene Ontology location is reachable by antibodies, with high confidence. PROTAC: it is named in the literature on targeted protein degradation; UniProt records ubiquitination sites on it; ubiquitination databases record sites on it; its protein half-life has been measured; a small molecule that binds it is known.
Target class: TKL protein kinase group; TKL protein kinase LRRK family; Enzyme; Kinase; Protein Kinase
Chemical probes: GNE7915 (high quality), HG-10-102-01 (high quality), JH-II-127 (high quality), LRRK2-IN-1 (high quality), Merck LRRK2 inhibitor-2 (high quality), XL01126
Gene: Protein-coding gene on chromosome 12 (40,196,744 to 40,369,285, forward strand). Ensembl gene ENSG00000188906.
Subcellular location: Cytoplasmic vesicle; Perikaryon; Golgi apparatus membrane; Cell projection, axon; Cell projection, dendrite; Endoplasmic reticulum membrane; Cytoplasmic vesicle, secretory vesicle, synaptic vesicle membrane; Endosome; Lysosome; Mitochondrion outer membrane; Cytoplasm, cytoskeleton; Cytoplasmic vesicle, phagosome
Subcellular location (Human Protein Atlas): Basal body; Vesicles; Cytosol; Nuclear membrane; Nucleoplasm
Pathways (Reactome):
Signal Transduction: PTK6 promotes HIF1A stabilization
Gene Ontology:
Molecular function: actin binding; clathrin binding; GTP binding; GTP-dependent protein kinase activity; GTPase activator activity; GTPase activity; identical protein binding; JUN kinase kinase kinase activity; kinase activity; magnesium ion binding; MAP kinase kinase kinase activity; peroxidase inhibitor activity; protein binding; protein homodimerization activity; protein kinase A binding; protein kinase activity; protein serine kinase activity; protein serine/threonine kinase activity; signaling receptor complex adaptor activity; small GTPase binding; SNARE binding; syntaxin-1 binding; transmembrane transporter binding; tubulin binding; beta-catenin destruction complex binding; and 3 more
Biological process: calcium-mediated signaling; cellular response to dopamine; cellular response to manganese ion; cellular response to oxidative stress; cellular response to reactive oxygen species; cellular response to starvation; COPII vesicle coating; determination of adult lifespan; endocytosis; endoplasmic reticulum organization; exploration behavior; Golgi organization; GTP metabolic process; intracellular distribution of mitochondria; JNK cascade; lysosome organization; MAPK cascade; mitochondrion localization; mitochondrion organization; negative regulation of autophagosome assembly; negative regulation of endoplasmic reticulum stress-induced intrinsic apoptotic signaling pathway; negative regulation of establishment of protein localization to mitochondrion; negative regulation of GTPase activity; negative regulation of macroautophagy; negative regulation of protein processing; and 71 more
Cellular component: amphisome; autolysosome; axon; caveola neck; cytoplasm; cytoplasmic side of mitochondrial outer membrane; cytoplasmic vesicle; cytosol; dendrite; dendrite cytoplasm; endoplasmic reticulum; endoplasmic reticulum exit site; endoplasmic reticulum membrane; extracellular exosome; extracellular region; Golgi apparatus; Golgi membrane; Golgi-associated vesicle; growth cone; Lewy body; lysosome; microvillus; mitochondrial membrane; mitochondrial outer membrane; mitochondrion; and 21 more
Genetic constraint (gnomAD): Loss-of-function variants: 182 observed, 264.4 expected, observed/expected ratio (o/e) 0.69, 90% interval 0.61 to 0.78. The upper end of that interval is the gene's LOEUF score, 0.78, which puts it in group 3 of 6, group 1 being the genes least tolerant of losing a copy. Missense variants: 2,592 observed, 2,834.6 expected, observed/expected ratio (o/e) 0.91, 90% interval 0.88 to 0.94. Synonymous variants: 987 observed, 1,001.5 expected, observed/expected ratio (o/e) 0.99, 90% interval 0.93 to 1.04.
Gene-disease validity (ClinGen):
ClinGen rates the evidence that LRRK2 causes each of these diseases.
Parkinson disease (autosomal dominant): Definitive. A progressive degenerative disorder of the central nervous system characterized by loss of dopamine producing neurons in the substantia nigra and the presence of Lewy bodies in the substantia nigra and locus coeruleus.
Homologues: Orthologues: chimpanzee LRRK2 (99% identical), macaque LRRK2 (97% identical), dog LRRK2 (92% identical), pig LRRK2 (90% identical), rabbit LRRK2 (87% identical), mouse Lrrk2 (87% identical), rat Lrrk2 (86% identical), guinea pig LRRK2 (85% identical), tropical clawed frog lrrk2 (63% identical), zebrafish lrrk2 (48% identical). Paralogues in human: LIMK2 (6% identical), LIMK1 (6% identical), TNNI3K (6% identical), KSR1 (5% identical), MAP3K9 (5% identical), KSR2 (5% identical), BRAF (5% identical), MAP3K10 (5% identical), TESK2 (5% identical), MAP3K21 (5% identical), TESK1 (5% identical), RAF1 (4% identical), and 11 more.
Diseases named in the same sentence as LRRK2 in open-access papers:
LRRK2 is named in the same sentence as 292 diseases in open-access papers, as found by Europe PMC text mining. Sharing a sentence is not in itself a finding about the gene and the disease. The quoted sentences say what the papers report.
Parkinson disease (1,156 papers, 2006 to 2026). "The endolysosomal phospholipid bis(monoacylglycerol)phosphate (BMP) is aberrantly elevated in urine from Parkinson's patients carrying mutations in leucine-rich repeat kinase 2 (LRRK2) and glucocerebrosidase (GCase)." (PMID 41925724, 2026). "Mutations in leucine-rich repeat kinase 2 (LRRK2) are the most common cause of familial Parkinson's disease, yet the molecular mechanism governing LRRK2 activation remains incompletely understood." (PMID 41674840, 2026). "LRRK2 contains a kinase domain where the N2081D Crohn’s disease (CD) risk and the G2019S Parkinson’s disease (PD) pathogenic variants are located." (PMID 41031878, 2025). "Common and rare variants in LRRK2 influence Parkinson’s disease (PD) risk across diverse populations." (PMID 40950508, 2025). "Aberrant increases in kinase activity of leucine-rich repeat kinase 2 (LRRK2) are associated with Parkinson’s disease (PD)." (PMID 39554022, 2025). "Substantial studies revealed the association of LRRK2 genetic variations with Parkinson’s disease as well as immune-mediated conditions like inflammatory bowel disease, leprosy, and tuberculosis." (PMID 39744510, 2025). "We study an inherited form of Parkinson’s disease that is caused by activating mutations in the leucine-rich repeat kinase 2 (LRRK2)." (PMID 39537338, 2025). "Our study extends previous findings on homotaurine’s effects by investigating its potential therapeutic role in NESC 3D colonies derived from Parkinson’s disease models, specifically those harboring the LRRK2-G2019S mutation." (PMID 40227236, 2025). "iPSC-based disease modeling demonstrates that neuromelanin and LRRK2 mutations cooperate to promote microglia-mediated dopaminergic neurodegeneration in Parkinson’s disease." (PMID 40796643, 2025). "Leucine-rich repeat kinase 2 (LRRK2) phosphorylates a subset of Rab GTPases that regulate receptor trafficking; LRRK2-activating mutations are linked to Parkinson’s disease." (PMID 40690364, 2025). "LRRK2 is a large and multifunctional serine/threonine-protein kinase, and mutations in its gene are the most common genetic predisposition for Parkinson’s disease." (PMID 40277885, 2025). "Background and Aims: Pathogenic variants in the LRRK2 gene are the most common monogenic cause of Parkinson's Disease (PD)." (PMID 40542572, 2025). "Whereas LRRK2 mutation carriers with Parkinson's disease reveal impaired presynaptic dopamine function, clinically asymptomatic, otherwise, healthy, mutations carriers reveal early increases in dopamine turnover by PET imaging." (PMID 40125558, 2025). "Leucine-rich repeat kinase 2 (LRRK2) phosphorylates a subset of Rab GTPases that regulate receptor trafficking, and LRRK2-activating mutations are linked to Parkinson’s disease." (PMID 40690364, 2025). "Variants in LRRK2 are associated with increased risk for Parkinson’s and Crohn’s disease (CD), including a putative protective haplotype (N551K-R1398H) linked to reduced risk for both PD and CD." (PMID 40770658, 2025). "Progress on these topics is critical for both understanding the cellular basis for Parkinson’s disease and for designing and testing new therapies that target LRRK2 and its associated biology." (PMID 40758897, 2025). "In this large sample of individuals with LRRK2-associated parkinsonism, we compared clinical, imaging and biofluid biomarker and genetic characteristics among those with evidence of CSF asyn aggregates compared with those without." (PMID 40114783, 2025). "Mutations in LRRK2 represent the most common genetic cause of both familial and sporadic Parkinson’s disease (PD)." (PMID 41377992, 2025). "Up to four follow-up visits (after baseline) were expected for 141 LRRK2-associated parkinsonism cases; the majority completed Year 4 [31 (69%) CSFasynSAA− and 78 (81%) CSFasynSAA+ cases]." (PMID 40114783, 2025).
Parkinson disease (continued). "A large number of animal models have been used in an attempt to understand LRRK2-linked Parkinsonism and mimic the disorder by either overexpressing or knocking out specific LRRK2 genes." (PMID 40332013, 2025). "PPM1H phosphatase reverses Parkinson's disease-associated, leucine-rich repeat kinase 2 (LRRK2)-mediated, Rab GTPase phosphorylation." (PMID 40912655, 2025). "LRRK2 mutations cause dominantly inherited familial Parkinson’s disease, and common variants contribute to sporadic Parkinson’s disease risk." (PMID 39812709, 2025). "Leucine-rich repeat kinase 2 (LRRK2) has become a critical drug target in Parkinson’s disease, with mutation-selective inhibitors offering promising potential for precision medicine." (PMID 40802138, 2025). "In Parkinson disease, LRRK2, a major genetic risk factor for PD, is known to negatively regulate protein synthesis via miRNA." (PMID 40993824, 2025). "Parkinson’s disease is characterized by loss of dopamine neurons that project to the dorsal striatum, and mutations in LRRK2 and GBA1 are the most common genetic causes of familial Parkinson’s disease." (PMID 40737317, 2025). "With respect to Parkinson’s disease, dual roles of Rabs 29 and 32 as LRRK2 activators and Parkinson’s disease risk genes highlights the broader importance of defining how and when such proteins are engaged in LRRK2 regulation." (PMID 41332754, 2025). "Mutations in LRRK2 are causal for Parkinson’s disease (PD) and genetically associated with several inflammatory diseases including Crohn’s disease (CD), leprosy and systemic lupus erythematosus (SLE)." (PMID 40394349, 2025). "The LRRK2 gene is a key contributor to the genetic risk of Parkinson's disease, and a priority drug target for the disorder." (PMID 40545679, 2025). "Emerging evidence links Parkinson’s disease (PD)-causing mutations in the leucine-rich repeat kinase 2 (LRRK2) gene to dysfunctional axonal transport." (PMID 40570189, 2025). "Increased kinase activity of leucine-rich repeat kinase 2 (LRRK2) is associated with Parkinson’s disease (PD)." (PMID 40465731, 2025). "In this study, we investigated the effects of homotaurine in 3D NESC organoid colonies affected by the LRRK2-G2019S mutation, a key mutation associated with Parkinson’s disease." (PMID 40227236, 2025). "This gap limits our understanding of how LRRK2 interprets the diverse stress signatures that arise both during normal lysosome homeostasis and under pathological conditions linked to Parkinson’s disease." (PMID 41332754, 2025). "The LRRK2 gene encodes the LRRK2 protein, a 288 kDa serine/threonine kinase and GTPase implicated in Parkinson’s disease (PD)." (PMID 40425780, 2025). "Conversely, LRRK2 variants associated with decreased risk for Parkinson’s and Crohn’s diseases exhibit reduced kinase activity." (PMID 39812709, 2025). "Mutations in LRRK2, a leading genetic cause of Parkinson’s disease (PD), are linked to immune dysregulation, but the immune profiles in the periphery and central nervous system (CNS) remain incompletely defined." (PMID 41309625, 2025). "In support of this idea, Basque individuals present higher prevalence of R1441G mutations in LRRK2 gene, the most frequent cause of Parkinson's disease." (PMID 39809916, 2025). "This study demonstrates that food-derived plasma metabolites are significantly altered in Parkinson’s disease and show subtype-specific associations with clinical severity, particularly in carriers of LRRK2 and GBA1 mutations." (PMID 41515898, 2025). "For instance, the LRRK2 kinase has been associated with the development of both Parkinson and inflammatory bowel diseases." (PMID 41255709, 2025). "Variants in the LRRK2 gene have been associated with Parkinson’s disease (PD) in humans and studies of model organisms suggest that orthologs of this gene protect against both age-related neurodegeneration and defects in neurodevelopment." (PMID 40371391, 2025).
Parkinson disease (continued). "Potential modes of increased LRRK2 expression in PSP can be derived from the physiologic functions of LRRK2 and findings in Parkinson disease where LRRK2 is an important risk factor." (PMID 40465013, 2025). "From a cohort of 654 Parkinson's disease patients who underwent genetic screening, 42 heterozygous carriers of LRRK2 mutations were identified." (PMID 40542608, 2025). "It is also worth noting that Rab12 is one of the physiological substrates of the leucine-rich repeat kinase 2 (LRRK2), a kinase whose hyperactivation is linked to Parkinson’s and Crohn’s diseases." (PMID 40486912, 2025). "More recently, Mn was found to increase LRRK2 expression, a protein associated with Parkinson’s Disease, in vitro and in vivo, while LRRK2 deletion in microglia reduced cytokine release in vitro." (PMID 41476579, 2025). "Neurons expressing common familial Parkinson’s disease-associated mutations in the leucine-rich repeat kinase 2 (LRRK2) exhibit defective autophagy." (PMID 40623183, 2025). "When two genes linked to increased Parkinson’s risk converge on a lysosome, LRRK2 mutation enhances lysosomal release of soluble GPNMB potentially contributing to synuclein pathology." (PMID 41406219, 2025). "The final analytic sample included 148 LRRK2-associated parkinsonism cases and a comparator group of 378 sporadic Parkinson’s disease CSFasynSAA+ (sPD) frequency matched to them by age and disease duration." (PMID 40114783, 2025). "Leucine-rich repeat kinase 2 (LRRK2) is one of the most common genetic causes of Parkinson’s disease (PD), with over five pathogenic LRRK2 mutations identified in both familial and sporadic PD cases." (PMID 40722695, 2025). "Mutations that increase LRRK2 kinase activity have been linked to Parkinson’s disease and Crohn’s disease." (PMID 39812709, 2025). "Increased activity of leucine-rich repeat kinase 2 (LRRK2) is an important risk factor for Parkinson’s disease." (PMID 41332754, 2025). "Expression of the G2019S mutant caused a more severe parkinsonism-like phenotype compared to equivalent expression levels of wild-type LRRK2." (PMID 40076730, 2025). "Parkinson’s disease–associated, activating mutations in the LRRK2 kinase block primary cilium formation in cell culture and in specific cell types in the brain." (PMID 39537338, 2025). "Here, we found that the most common Parkinsonism gene mutation, LRRK2 G2019S, enhances the phosphorylation of the ERM proteins (Ezrin, Radixin, and Moesin), components of the perisynaptic astrocyte processes in a subset of cortical astrocytes." (PMID 39253496, 2025). "STING-induced autophagy promotes endolysosomal biogenesis through activation of the MiT/TFE transcription factors and the kinase LRRK2, which has been linked to Parkinson’s disease." (PMID 39982740, 2025). "This study represents the first investigation into the association between LRRK2 gene mutations and Parkinson’s disease (PD) in the Emirati population." (PMID 41383818, 2025). "Mutations in Leucine-Rich Repeat Kinase 2 (LRRK2) constitute the predominant genetic cause of Parkinson’s disease, with the most common mutations leading to a constituently active LRRK2." (PMID 40801573, 2025). "Some mutations are located in the kinase domain and have been linked to increased enzymatic activity of LRRK2, which contributes to the pathogenesis of Parkinson’s disease (PD)." (PMID 41471279, 2025). "This supports future studies to define physiological and pathophysiological consequences of excessive LRRK2 activity arising from lysosome damage and Parkinson’s disease–related mutations." (PMID 40758897, 2025). "MacLeod D.A., Rhinn H., Kuwahara T., Zolin A., Di Paolo G.,MacCabeB.D., Marder K.S., Honig L.S., Clark L.N., Small S.A.,Abeliovich A. Rab7L1 interacts with LRRK2 to modify intraneuronalprotein sorting and Parkinson’s disease risk." (PMID 41164274, 2025).